LRRC15 (leucine rich repeat containing 15)
Diseases named in the same sentence as LRRC15 in open-access papers (continued):
Sharing a sentence is not in itself a finding about the gene and the disease.
COVID-19 (4 papers, 2022 to 2023). A disease caused by infection with severe acute respiratory syndrome coronavirus 2. "Severe COVID-19 is associated with substantial inflammation and other changes to the lungs, which could influence how LRRC15 is distributed as infection progresses." (PMID 36735681, 2023). "Given that our experiments pointed to LRRC15 as an antiviral restriction factor, we sought to specifically investigate whether LRRC15 is associated with viral burden and disease progression in COVID-19 patients." (PMID 36228039, 2022). "Notably, two studies of COVID-19 patient cohorts independently uncovered associations with LRRC15." (PMID 36735681, 2023). "Because lung tissue is the main source of severe COVID-19 symptoms and expresses among the highest levels of LRRC15 in the body, we conducted a more detailed analysis of LRRC15 expression within the lungs using public single-cell transcriptomic datasets." (PMID 36735681, 2023). "In an analysis of lung tissue samples to find transcriptional signatures of fatal COVID-19, LRRC15 was found to be significantly higher in fatal COVID-19 cases compared to controls." (PMID 36735681, 2023). "We also observed lung LRRC15+ myofibroblasts in multiple COVID-19 patient datasets, and these cells also express collagen." (PMID 36757924, 2023). "Analysis of human lung single-cell RNA sequencing dataset reveals that expression of LRRC15 is primarily detected in fibroblasts and particularly enriched in pathological fibroblasts in COVID-19 patients." (PMID 36228039, 2022). "Consistent with our analyses of non-COVID-19 lungs, we found that fibroblasts and lymphatic endothelial cells had the highest levels of LRRC15 expression." (PMID 36228039, 2022). "Two independent single-cell RNA-sequencing (scRNA-seq) datasets of non-COVID-19 human lungs revealed that LRRC15 was predominantly expressed in a subset of fibroblasts and lymphatic endothelial cells." (PMID 36228039, 2022). "A notable finding was the identification of plasma levels of LRRC15 as a marker of COVID-19 severity." (PMID 36522333, 2022). "In lungs from COVID-19 patients, the scRNA-seq data revealed that LRRC15-expressing fibroblasts and endothelial cells significantly outnumbered ACE2-expressing epithelial cells." (PMID 36228039, 2022). "We identify plasma levels of the proposed alternative SARS-CoV-2 receptor, LRRC15, as a marker of COVID-19 severity." (PMID 36522333, 2022). "Both lasso and random forests identified plasma LRRC15 protein levels as the most important biomarker of COVID-19 severity." (PMID 36522333, 2022). "To explore the clinical relevance of LRRC15 to COVID-19 pathophysiology, we analyzed 2 independent scRNA-seq datasets of lungs from deceased COVID-19 patients." (PMID 36228039, 2022). "Molecular interactions between SARS-CoV-2 and its host dictate the course of COVID-19 disease progression; this study identifies LRRC15 as a new fibroblast SARS-CoV-2 spike receptor that can block infection, activate cellular antiviral programs, and suppress collagen production." (PMID 36757924, 2023). "Levels of LRRC15 were greatly elevated by inflammatory signals in the lungs of COVID-19 patients." (PMID 36735681, 2023). "A systematic search for human proteins that can bind to the spike protein of SARS-CoV-2 reveals that LRRC15 can act as a host factor for the virus, and may therefore modulate infection with potential implications for COVID-19." (PMID 36735681, 2023). "LRRC15 is induced extensively during COVID-19, where it lines the airways and may form an innate antiviral barrier." (PMID 36757924, 2023). "These fibroblast and endothelial populations where LRRC15 is most abundant have clear significance to COVID-19 pathology, but it will be important to determine how LRRC15 may be involved in disease pathways where these cell types are associated." (PMID 36735681, 2023).
COVID-19 (continued). "This unexpected interaction merits further investigation to determine how SARS-CoV-2 exploits host LRRC15 and whether it could account for any of the distinctive features of COVID-19." (PMID 36735681, 2023). "We found LRRC15 expression caused an up-regulation of 3 antiviral pathways, IFIT, MX, and OAS, and these antiviral pathways are also up-regulated in primates infected with SARS-CoV-2 and COVID-19 patients." (PMID 36757924, 2023). "Although our investigations so far have only just begun to reveal what roles LRRC15 may have in COVID-19, there is considerable potential for dissecting how LRRC15 acts during infection that builds off the molecular binding mechanism we elucidate here." (PMID 36735681, 2023). "Importantly, while this article was under review, a multiomics study identified LRRC15 as a strong predictor of COVID-19 severity in human patients in a preprint." (PMID 36228039, 2022). "Interestingly, the relative levels of LRRC15 in COVID-19 patients have been reported to correlate to a patient’s viral burden, implying that this induction of LRRC15 expression may be consequential to infection." (PMID 36735681, 2023). "More broadly, there were increases in both LRRC15 and ACE2 levels in COVID-19 patients, suggesting that a common response pathway may expand the role of both during infection." (PMID 36735681, 2023). "Of note, SARS-CoV-2 infection of lung epithelial cell lines in vitro did not lead to significant changes in LRRC15 expression, which is consistent with our prior analyses pointing to a fibroblast-specific role of LRRC15 in COVID-19." (PMID 36228039, 2022). "Of note, data mining of external studies revealed similar findings in two other studies that measured LRRC15 in non-ESKD COVID-19 patients." (PMID 36522333, 2022). "Moreover, we found that LRRC15 is present on the alveolar surface of lung tissue samples from donors with COVID-19, but not present in control lungs from individuals without COVID-19, and LRRC15 expression was mutually exclusive with collagen." (PMID 36757924, 2023). "LRRC15 is primarily expressed in innate immune barriers including placenta, skin, and lymphatic tissues as well as perturbed-state tissue fibroblasts, and we found LRRC15 protein is absent in control lungs, but highly expressed in COVID-19 patients, where it lines the airways." (PMID 36757924, 2023). "In summary, we show LRRC15 physically links SARS-CoV-2 to perturbed-state fibroblasts, where LRRC15 expression can control the balance between fibrosis and antiviral responses, and this activity may help promote COVID-19 resolution while preventing COVID-19 lung fibrosis." (PMID 36757924, 2023). "If lung LRRC15/SARS-CoV-2 complexes are depleted, and new LRRC15 is not produced, this may lead to a detectable decrease in serum LRRC15 that is indicative of poor COVID-19 outcome." (PMID 36757924, 2023).
idiopathic pulmonary fibrosis (4 papers, 2022 to 2023). Idiopathic pulmonary fibrosis (IPF) is a nonneoplastic pulmonary disease that is characterized by the formation of scar tissue within the lungs in the absence of any known cause. "CTHRC1 (collagen triple helix repeat containing 1) is a gene whose expression defines pathogenic fibroblasts in SSc and idiopathic pulmonary fibrosis (IPF) fibrotic lung specimens and is a marker along with LRRC15 for myofibroblasts across tissues." (PMID 36490328, 2022). "To investigate whether Lrrc15+ MSCs exhibit therapeutic potential for cell transplantation, we prepared a pulmonary fibrosis (PF) model by intratracheal injection of bleomycin." (PMID 37534184, 2023). "The LRRC15-positive MSC populations in human and mouse bone marrow tissues highly expressed stemness-associated transcription factors and therapeutic cytokines, and showed better therapeutic effect in bleomycin-induced pulmonary fibrosis model mice." (PMID 37534184, 2023). "To further examine whether LRRC15+ MSCs possess therapeutic function, we performed cell transplantation in a bleomycin-induced pulmonary fibrosis (BPF) model, which is one of the most established drug-inducible disease models." (PMID 37534184, 2023). "Moreover, LRRC15 is found on collagen-producing myofibroblasts, and we show ectopic expression of LRRC15 suppresses collagen production and drives antiviral programs, and in this way, directly links SARS-CoV-2 with innate antiviral immunity and lung fibrosis." (PMID 36757924, 2023).
melanoma (4 papers, 2023 to 2025). A malignant, usually aggressive tumor composed of atypical, neoplastic melanocytes. "Furthermore, gene expression of LRRC15 and TWIST1 clearly does not correlate in several cancer types such as adrenocortical carcinoma or melanoma." (PMID 37534184, 2023).
soft tissue sarcoma (4 papers, 2020 to 2025). A malignant neoplasm arising from muscle tissue, adipose tissue, blood vessels, fibrous tissue, or other supportive tissues excluding the bones. "Preclinical data demonstrated that targeting LRRC15 with the antibody–drug conjugate ABBV-085 produced substantial anti-tumor effects in LRRC15-positive soft-tissue sarcoma (STS) models." (PMID 40940809, 2025). "We report here the first large study assessing LRRC15 expression in mesenchymal malignancies (soft-tissue sarcomas) and its potential therapeutic application in this indication." (PMID 32210091, 2020). "This is the first focused examination of LRRC15 expression and ABBV-085 activity in soft-tissue sarcomas (STS)." (PMID 32210091, 2020). "Analysis of Leucine-Rich Repeat Containing 15 (LRRC15) expression across 711 soft-tissue sarcoma (STS) cases revealed that, unlike in epithelial tumors, LRRC15 is present not only in stromal cells but also in tumor cells in various STS subtypes." (PMID 40940809, 2025).
Arthritis (3 papers, 2022 to 2025). Inflammation of a joint. "Cluster 5 contains the bulk of the mouse S2d(Dkk3/Lrrc15+) SLSFs and M5 is linked to human cells in both clusters 5 and 6, suggesting that both human clusters (H5 and 6) likely acquire the “intermediate” arthritis-specific profile previously identified in hTNFtg SF states." (PMID 35879783, 2022). "Silencing of Lrrc15 reduced the soft tissue swelling and arthritis index compared with CIA + Ad‐scramble rats." (PMID 40642947, 2025). "Single-cell analysis of fibroblast lineages showed that LRRC15+ cells were enriched in arthritis, skin wound, fibrosis, and small and large pancreatic ductal adenocarcinoma, and these cells also showed high expression of CTHRC1." (PMID 37311583, 2023). "The development of arthritis leads to shrinkage of homeostatic SFs and favors the emergence of SF profiles marked by Dkk3 and Lrrc15 expression, functioning towards enhanced inflammatory responses and matrix catabolic processes." (PMID 35879783, 2022). "Concomitantly with the shrinkage of the stably present SLSFs, we observed the emergence of arthritis-specific Thy1+ SF subpopulations (Dkk3/Lrrc15+ and Birc5/Aqp1+), accompanied by expansion of Prg4high/Thy1-LSFs." (PMID 35879783, 2022).
bladder cancer (3 papers, 2019 to 2023). "LRRC15+ myCAFs were associated with poor response to anti-PD-L1 treatment in bladder cancer trial of atezolizumab." (PMID 36313650, 2022).
head and neck cancer (3 papers, 2023 to 2025). A primary or metastatic malignant neoplasm affecting the head and neck. "Leucine-Rich Repeat-Containing Protein 15 (LRRC15): LRRC15 is upregulated in CAFs from breast, lung, pancreatic, and head and neck cancers." (PMID 41441395, 2025). "The abundance of CAFs positive for LRRC15+ (leucine-rich repeat-containing 15) is correlated with poor outcomes following immunotherapy across six cancer types, such as renal cell carcinoma, head and neck cancer, and NSCLC." (PMID 37199594, 2023).
osteoarthritis (3 papers, 2021 to 2024). A noninflammatory degenerative joint disease occurring chiefly in older persons, characterized by degeneration of the articular cartilage, hypertrophy of bone at the margins and changes in the synovial membrane. "Recent studies identified that LRRC15 was an important factor contributing to cartilage damage in osteoarthritis." (PMID 36317112, 2022). "The authors’ study identified leucine rich repeat containing 15 (LRRC15) and secreted phosphoprotein 1 (SPP1) as hub genes in calcific aortic valve disease (CAVD) and osteoarthritis (OA) and found that they were related to immune processes." (PMID 38566328, 2024).
pancreatic adenocarcinoma (3 papers, 2022 to 2024). "In tumorigenesis of pancreatic adenocarcinoma, the formation of leucine-rich-repeat-containing protein 15(LRRC15)+ CAF is increased by TGF-β signaling." (PMID 36700220, 2022).
pancreatic ductal adenocarcinoma (3 papers, 2021 to 2023). An infiltrating adenocarcinoma that arises from the epithelial cells of the pancreas. "In pancreatic ductal adenocarcinoma, increased levels of the myCAF (LRRC15+) signature correlated with poor response to anti-PD-L1 therapy in an immunotherapy clinical trial." (PMID 34869001, 2021).
breast invasive carcinoma (2 papers, 2012 to 2024). "LRRC15 by EWSR1-WT1 (+KTS) is strongly expressed in invasive breast cancer cell line and possibly contributes to the invasive phenotype of DSCRT." (PMID 22587803, 2012).
breast tumor (2 papers, 2017 to 2024). "Subsequently, it was reported that LRRC15 mRNA exhibited a high expression exclusively in breast tumor tissues, with a weak expression observed in other healthy tissues, except for placental tissue." (PMID 38611080, 2024). "LRRC15 showed a strong expression in breast tumor tissues (100%), with +2 staining in 1% of the tissues and +3 staining in 99%, while EFNA3 exhibited strong positivity in 90% of the tissues, ranging from 0 (10%), +1 (17%), +2 (22%), to +3 (51%)." (PMID 38611080, 2024). "LEF1 enhancer facilitated Wnt pathway in tumor invasion, while LRRC15 protein, which was usually over-expressed in tumor, particularly breast tumors, was reported as a potential drug target for virus based cancer therapy." (PMID 28950860, 2017). "Based on these factors, LRRC15, EFNA3, TSPAN13, and CA12 were identified as transcripts with higher expression and prevalence levels in breast tumors, with low expressions in most of the control tissues." (PMID 38611080, 2024).
colorectal cancer (2 papers, 2025). A primary or metastatic malignant neoplasm that affects the colon or rectum. "In the HA-rich colorectal cancer model, the cancer-associated fibroblast (CAF)-directed AbEn, TAVO423 (FAP × LRRC15 × HYAL trispecific antibody) achieved greater intratumoral HA depletion resulting in superior tumor growth inhibition compared to untargeted HYAL." (PMID 41228205, 2025). "To investigate whether [177Lu]Lu-DUNP19 therapy could synergize with immune checkpoint inhibitors, we combined [177Lu]Lu-DUNP19 RIT with immune checkpoint blockade (anti-CTLA4 + anti-PD1) in the syngeneic MC38 colorectal cancer model (LRRC15- cancer cells, LRRC15+ stroma)." (PMID 41022704, 2025). "TAVO423 is a FAP × LRRC15 × HYAL trispecific AbEn that effectively degraded HA, delayed tumor growth, and enhanced the efficacy of various therapeutics in an in vivo HA-rich colorectal cancer model." (PMID 41228205, 2025).
glioma (2 papers, 2021 to 2025). A benign or malignant brain and spinal cord tumor that arises from glial cells (astrocytes, oligodendrocytes, ependymal cells). "Furthermore, the prognosis correlation and immune characteristics of LRRC15 were validated using the Chinese Glioma Genome Atlas (CGGA) database and our clinical tissues by immunochemistry assay." (PMID 33960636, 2021). "In flow cytometry assays using U-87 MG human glioma cells expressing both FAP and LRRC15, the dual-targeted antibody demonstrated increased binding (EC50 = 0.2645 nM vs. 12.68 nM and 0.8885 nM) compared to the FAP-only mAb (EC50 = 12.68 nM) and LRRC15-only mAb (EC50 = 0.8885 nM) controls." (PMID 41228205, 2025).
viral infection (2 papers, 2022 to 2023). "The coculture of ACE2+LRRC15− cells and ACE2-LRRC15+ cells exhibited a significant suppression of viral infection with spike proteins of 2 different SARS-CoV-2 variants." (PMID 36228039, 2022). "Despite emerging independently from a genome-wide screen, LRRC15 shared similarities to the tissue distribution of ACE2, with major targets of viral infection such as the lungs and gastrointestinal tract also showing the most abundant expression of LRRC15." (PMID 36735681, 2023). "Elucidating what function LRRC15 has evolved for within these hosts could provide a critical clue to determining how this interaction acts during viral infection." (PMID 36735681, 2023). "At 2 different titers of viral infection, the similar pattern of reduction was observed and coculturing with DC-SIGN-expressing cells did not induce the reduction, confirming the specificity of inhibitory function of LRRC15." (PMID 36228039, 2022). "Collectively, these results highlight the trans-inhibitory function of LRRC15 proven using a coculture model, suggesting that expression of LRRC15 in SARS-CoV-2-nonpermissive fibroblasts protects permissive cells against viral infection in the lung." (PMID 36228039, 2022).
adenovirus infection (1 paper, 2023). "In previous work, LRRC15 has been shown to suppress adenovirus infection, and here, we show LRRC15 can also bind to and suppress SARS-CoV-2 spike pseudovirus and live SARS-CoV-2 infection." (PMID 36757924, 2023).
Alzheimer disease (1 paper, 2017). A progressive, neurodegenerative disease characterized by loss of function and death of nerve cells in several areas of the brain leading to loss of cognitive function such as memory and language. "The role of LRRC15 in inflammation is also proposed, as it is induced by beta-amyloid and pro-inflammatory cytokines in astrocytes of Alzheimer's disease brain and up-regulated by pro-inflammatory stimuli during the process of dental caries." (PMID 29137139, 2017).
atopic dermatitis (1 paper, 2025). "LRRC15 was evident in inflammation with scarring risk (inflamed hidradenitis suppurativa skin) but not in noninflamed skin or inflamed skin without scarring risk (atopic dermatitis skin)." (PMID 40993240, 2025).
cervical tumors (1 paper, 2022).
gastric cancer (1 paper, 2022). A primary or metastatic malignant neoplasm involving the stomach. "The presence of tumor-specific activated stromal cells in our data suggest the applicability of cell type depletion strategies that are currently under development such as LRRC15 and CCR8 antibody drug conjugates in gastric cancer." (PMID 36550535, 2022).
gastrointestinal stromal tumor (1 paper, 2020). "We analyzed LRRC15 protein expression by IHC in 711 cases of STS, including gastrointestinal stromal tumors (GIST)." (PMID 32210091, 2020).
leiomyosarcoma (1 paper, 2020). An uncommon, aggressive malignant smooth muscle neoplasm, usually occurring in post-menopausal women. "The proportion of LRRC15-positive cases differed significantly according to histological subtypes with staining observed in 51%, 47%, and 36% of UPS, dedifferentiated liposarcomas and leiomyosarcomas, respectively (p = 0.003)." (PMID 32210091, 2020).
lung carcinoma (1 paper, 2024). "In lung cancer, ITGB4 might be related to leucine-rich repeat-containing protein 15 (LRRC15), which is involved in cell-cell and cell-matrix interactions and overexpressed in mesenchymal-derived tumors, exerting a metastatic invasion role in lung cancer." (PMID 39228892, 2024).
mesenchymal tumors (1 paper, 2020). "By analyzing a small cohort of 39 STS, we have also observed that LRRC15 can also be directly expressed on cancer cells from mesenchymal tumors." (PMID 32210091, 2020).